IGKJ1 (immunoglobulin kappa joining 1)
Description:
J region of the variable domain of immunoglobulin kappa light chains that participates in the antigen recognition. Immunoglobulins, also known as antibodies, are membrane-bound or secreted glycoproteins produced by B lymphocytes. In the recognition phase of humoral immunity, the membrane-bound immunoglobulins serve as receptors which, upon binding of a specific antigen, trigger the clonal expansion and differentiation of B lymphocytes into immunoglobulins-secreting plasma cells. Secreted immunoglobulins mediate the effector phase of humoral immunity, which results in the elimination of bound antigens. The antigen binding site is formed by the variable domain of one heavy chain, together with that of its associated light chain. Thus, each immunoglobulin has two antigen binding sites with remarkable affinity for a particular antigen. The variable domains are assembled by a process called V-(D)-J rearrangement and can then be subjected to somatic hypermutations which, after exposure to antigen and selection, allow affinity maturation for a particular antigen.
Synonyms: J1
Gene: Immunoglobulin joining (J) gene on chromosome 2 (88,861,886 to 88,861,923, reverse strand). Ensembl gene ENSG00000211597.
Subcellular location: Secreted; Cell membrane
Gene Ontology:
Cellular component: extracellular region; plasma membrane